CD44 (CD44 molecule (IN blood group))
Diseases named in the same sentence as CD44 in open-access papers (continued):
Sharing a sentence is not in itself a finding about the gene and the disease.
tumor (continued). "HA binding to CD44 is involved in the stimulation of both receptor kinases (e.g., ErbB2, EGFR and TGFβ receptors) and non-receptor kinases (e.g., c-Src and ROK) required for a variety of tumor cell-specific functions leading to tumor progression." (PMID 24606718, 2014). "After sorting by flow cytometry, we obtained four subgroups (Sca-1+-CD44+, Sca-1+-CD44-, Sca-1--CD44+ and Sca-1--CD44-) of tumor-retrieved cells from the Non-Rec and Rec group." (PMID 24581230, 2014). "For example, only 6- to 40-mers, but not native HA, can induce CD44 cleavage, promote tumor cell motility in a CD44-dependent manner, or activate MMPs." (PMID 25358954, 2014). "The reduction on the tumor cell surface CD44 was due to the catalytic activity of the protease, since CD44 gene expression was not affected by arazyme treatment in both tumor cell lines." (PMID 24788523, 2014). "In line with this notion, our results clearly show that the combination of 2-DG and radiation elicits anti-tumor immune response by not only restoring the levels of CD4+ cells, but also the levels of molecules related to its signaling i.e. CD44, CD69, CD45, TCR-β, TCR-γδ and CD28." (PMID 25248151, 2014). "The authors reported that 200–500 EpCAMhigh/CD44+ cells promoted tumorigenesis in non-obsese diabetic/severe combined immunodeficient mice, while no tumor was produced by injection of 104 EpCAMlow/CD44− cells." (PMID 24765173, 2014). "The tumor subspheres expressed GFAP, CD133, Nestin, Nanog, CD44, and CD90." (PMID 24432012, 2014). "Sphere formation in serum-free suspension cultures has been well established as a means to enrich for cells with CSC-like properties, including drug resistance, self-renewal capability, high expression of stem cell markers (e.g., CD44, ALDH and BMI1), tumor initiation, and differentiation capacity." (PMID 25471937, 2014). "In our previous studies, we identified that OPN may interact with CD44 to induce CD44 cleavage, possibly through increased expression of both β-catenin and cyclin D1 in GIST tumor tissues." (PMID 24947165, 2014). "Correlation between CD44 expression and tumor depth did not quite reach a significant value (P >0.5)." (PMID 24491153, 2014). "In addition to tumor growth, expression of the cancer stem cell (CSC) marker CD44, and the human epidermal growth factor receptor 2 (HER 2) was tested." (PMID 25485633, 2014). "Histological analysis indicated the absence of tumor cells in the thymus while flow cytometry analysis using CD44 and CD25 antibodies indicated that thymi contained a normal profile of immature DN thymocytes typical for mice with the PrkdcScid/Scid mutation." (PMID 24586935, 2014). "Unlike normal primary cells, tumor-derived cells express CD44 in a high-affinity state, which is thus capable of binding and internalizing HA." (PMID 24642908, 2014). "Comparable percentages of the Sca-1+-CD44+ subgroup were observed between the Rec and Non-Rec groups (63.2 vs. 20.5%), suggesting that this subgroup of cells played a role in tumor recurrence." (PMID 24581230, 2014). "Since the normal basal layer of epithelium was c-kit positive like the neoplastic component, we suggest that this tumor could derive from pluripotent-like cells, also with the support of high positivity for nestin, CD133, and CD44." (PMID 24959179, 2014). "To determine whether CD44 or CEA expression of tumor cells is an important factor for the overall survival of SCLC patients, we used tumor micro arrays (TMA) of clinical biopsies." (PMID 24699516, 2014). "Though ALT-803 lost its antimyeloma activity in tumor-bearing IFN-γ knockout mice, it was able to retain its ability to promote CD8(+)CD44(high) memory T-cell proliferation, indicating that ALT-803-mediated stimulation of CD8(+)CD44(high) memory T-cells is IFN-γ-independent." (PMID 24896845, 2014). "In our study, the frequency of CD44 positive cells in tumor samples was 60 % and all non- tumoral samples were negative." (PMID 25635255, 2014).
tumor (continued). "Moreover, these miRNAs suppress tumor cell formation, expression of cancer stem cells (CSC) markers, and stemness factors such as CD133, CD44, Oct4, C-Myc, and K1f4 in PC-3 cells, ultimately preventing bone invasion and tumorigenicity." (PMID 25147739, 2014). "Nestin, CD44, and CD133 antigens, markers of stem cell properties, were overexpressed in the neoplasm and could suggest a tumor origin by pluripotent stem cells." (PMID 24959179, 2014). "Immunohistochemistry of tumor tissue sections obtained from PANC-1 xenografts reveals that the single treatments reduced the expression of the ALDH1, CD44, Sox2, CxCR4 and Ki-67, and induced cleavage of Caspase-3, whereas both treatments together had strongest effects." (PMID 25015789, 2014). "These CD44-positive CSCs harbor enhanced clonogenicity, tumor-initiating and metastatic properties and are also depleted in miR-34a expression, compared to CD44-negative CSCs." (PMID 25019555, 2014). "Dual expression of CD44 and ALDH in SCC tissue sections may be more intense toward the center of tumor nodules." (PMID 24019906, 2013). "In any case, in both scenarios the CD44 VE expression level of the true metastatic clone is not immediately obvious from the overall expression of the primary tumour, which partially explains the contradicting results described in the literature." (PMID 23342032, 2013). "Tumors derived from secondary and tertiary xenografts of THJ-11T cells consistently reproduced the primary tumors at the histological level, and Western blotting and immunohistochemical analysis confirmed the expression of tumor markers ALDH, CD44 and CXCR4 in the xenografts." (PMID 23724124, 2013). "Similarly, an antibody directed against CD44, H90, has demonstrated efficacy in an AML model by specifically targeting CICs leading to promotion of differentiation, and inhibition of tumor proliferation and niche localization." (PMID 23314952, 2013). "Furthermore, tumours from the TP53INP1, LATS2 and CD44 silencing group showed increased cell proliferation as indicated by the strong staining of Ki67, compared with that of the MIA-V group." (PMID 23857777, 2013). "In contrast, none of the CD44+CD24neg tumours formed metastasis (0/19 animals), (representative images and graphed bioluminescence from metastasis)." (PMID 23982961, 2013). "The survival of patients with positive expression of CD44 or CD133 in tumor tissue was much shorter than that of patients with negative expression." (PMID 23874550, 2013). "This size difference can possibly be explained by the fact that by next generation sequencing on the same tumour, we identified a daunting number of small deletions across the CD44 isoforms (data not shown)." (PMID 23342032, 2013). "After >10 passages, the majority of the PPT2 cells expressed cell surface markers commonly used for the isolation of tumor-initiating cells from different types of human cancer, including CD133, CD44, CD44v6, EpCAM, CD166, CD49f, and presently, they retain these features after more than 26 passages." (PMID 24086245, 2013). "One hundred CD44+CD24low+ DT-22 cells formed tumours in only 3/8 mice (37.5%) with no further tumours emerging over the next ten months of observation." (PMID 23982961, 2013). "Studies from several investigators revealed that tumor-initiating cells are negative for AR and p63 and expressed the stem cell markers Oct-4, Nanog, Sox-2, Nestin, CD44, CD133, and CD117." (PMID 23936768, 2013). "Despite demonstrating that the tumourigenic potential lay within the CD44+ cell population, the large number of cells needed to initiate tumours (5000) indicated that the CD44+ subpopulation was not a pure CSC population." (PMID 23533441, 2013). "Although AD-01 up regulates CD44 expression, it appears to mediate an anti-migratory phenotype on CD44 positive cells, without effecting tumour or endothelial cell proliferation." (PMID 23457460, 2013).
tumor (continued). "It binds to CD44 and inhibits lung colonization of tumor cells in vivo but does not inhibit tumor cell proliferation when added to the culture medium." (PMID 23527117, 2013). "Furthermore, a recent report showed that both the CD44− and CD44+ cells of clinical HNSCC specimens possess similar sphere-forming and tumor-initiating capabilities, as well as chemoresistance." (PMID 23626764, 2013). "Lo KW and co-workers have recently demonstrated that CD44 and SOX2 expression are enriched in C666-1 tumor sphere forming cells which may serve as the potential candidate stem cell markers for the NPC C666-1 cells." (PMID 24156782, 2013). "YB-1 regulates the tumor-initiating cell markers, CD44 and CD49f however its role in Notch signaling has not been explored." (PMID 23593654, 2013). "CD44 can also interact with other ligands including growth factor receptors such as EGFR2 and PDGFR, osteopontin, collagens and matrix metalloproteinases (MMPs) which are involved in tumor progression and metastasis." (PMID 23947765, 2013). "We first examined the localization of MT1-MMP and CD44 on the surface of WM239 tumor cells plated directly on Matrigel with no endothelial cell layer, and found that these molecules did co-localize (not shown)." (PMID 24194929, 2013). "RO4929097 treatment, initiated when tumours reached 70 mm3, significantly inhibited growth of CD44+CD24low+-derived xenografts but not those arising from CD44+CD24neg cells." (PMID 23982961, 2013). "As a result of TNFα + Estrogen + EGF stimulation, new cell subtypes have dominated the tumor cell population, expressing high levels of VLA6 and of the metastasis-related adhesion molecules CD44 and β1, accompanied by high levels of CXCL8, CCL2, and MMPs that were released by the cells." (PMID 24369447, 2013). "In both studies, immunostaining with CD44 antibodies detecting all expressed CD44 isoforms in tumor tissue together (pan CD44 antibodies) was not a prognostic indicator." (PMID 23565227, 2013). "Notch inhibition reduced Sox2, sphere and colony formation, and in vivo tumour growth exclusively in the CD44+CD24low+ population, without affecting global cell proliferation." (PMID 23982961, 2013). "The CD44 isoform V6 was specifically restricted to melanospheres, being not expressed in differentiated cells, nor in tumor cells freshly isolated from melanosphere-derived xenografts nor in melanocytes." (PMID 24238212, 2013). "RT-qPCR analysis on elderly HCCs demonstrated that the high expression levels of 7 putative hepatic stem/progenitor cell biomarkers (including keratin 19 (K19), ABCG2, CD44, Nestin, CD133, EPCAM and OV6), is related to tumor angiogenesis and a poor prognosis for the HCC." (PMID 24160375, 2013). "The prevalence of a CD44+/CD24-/low tumor cell did not correlate with the event-free and overall survival and did not affect the tumor response to different treatment modalities." (PMID 23799994, 2013). "Of note, cytospins from detached tumor cell suspensions (just prior to cell implantation) also demonstrated a high degree of immunoreactivity to CD44 (data not shown)." (PMID 23385555, 2013). "Since CD44+CD24low+ MDA-MB-231 cells generated metastatic tumours, while none emerged from CD44+CD24neg cell injections, we investigated the importance of Notch activation in the CD44+CD24low+ population to cell migration and invasion." (PMID 23982961, 2013). "We noticed that the enforced overexpression of miR200c in the CD44+CD117+CSCs significantly reduced the expressions of both ZEB1 and Vimentin, but increased the expression of E-cadherin in the RNA and the protein levels in tumor samples." (PMID 23842108, 2013). "Among the CSC markers tested, the cells were negative for CD133, and 3.4% of the tumor cells were positive for CD44 (data not shown)." (PMID 23626764, 2013).
tumor (continued). "Eight weeks post-injection, 103 CSC cells successfully formed a tumor (2/4), while non-CD44+/CD24- tumor cells failed to form tumors until attaining 106 cells (1/4) (P<0.05, Fisher’s extract test, Fig. 1B1 and B2)." (PMID 23056395, 2012). "Intriguingly, 70.8% of BMI1-positive tumours in the present study also expressed CD44 strongly (data not shown)." (PMID 23046527, 2012). "It was rather supported by other studies indicating CD44 role in tumour invasion but with no clear information about metastasis." (PMID 22693526, 2012). "Others have shown that CD44+/CD24− cell lines contain these tumor-initiating cells, but we did not specifically focus on these stem cell-like cells or explicitly select for them." (PMID 22235336, 2012). "To determine the expression of known CSCs markers in TRICs, we carried out in vivo studies and used flow cytometry to analyze the proportion of GFP+ tumor cells in residual and vehicle-treated tumors that express the previously reported NSCLC CSC markers, CD133, CD44 and CD117." (PMID 23115623, 2012). "CD44 or CD147-KD could effectively inhibit tumor growth and reduce tumor volume and MVD combined with DTX treatment." (PMID 22870202, 2012). "Tumours with high CD44 and low ALDH1 expression had the poorest LRFS, whereas ALDH1 overexpressing tumours with lack of CD44 expression had the best LRFS." (PMID 22333601, 2012). "However, other studies have also shown that CD44+/CD24− cancer stem cells can evolve from ER-positive cells, and that estrogen induces expansion and tumor initiation activity of cancer stem cells." (PMID 22905168, 2012). "Found in a variety of cancers and identified by the marker CD44, these tumor-initiating cells can be sorted and propagated as non-adherent tumorspheres in suspension culture." (PMID 23155468, 2012). "In addition, the majority of the CD44/Sca1+ lung cells also expressed the surface markers CD24, ESA, or estrogen receptor (ER) at levels comparable with those expressed by primary tumor cells." (PMID 22277639, 2012). "Knock-down of CD44 or CD24 may enhance CSC differentiation to mature cells and reduce tumour progression." (PMID 22693526, 2012). "Although the role of CD44, with its multiple isoforms, in tumor progression appears complex and is not completely understood, binding of HA clearly induces CD44 clustering and activation." (PMID 24213471, 2012). "Using this method, we found that CD44+/CD24− cells were typically arranged in small clusters (10–15 cells), often located at the periphery of the tumour, adjacent to the surrounding stroma, while the CD44−/CD24+ cells were usually found in the central portion of the tumour." (PMID 23028444, 2012). "Metastatic tumor cell number in early metastatic regional lymph nodes on post-operative day 42 was distinctly decreased in the CD97/EGF1,2,5kd group as compared with the SGC-NS group, and was accompanied with the downregulation of CD44, VEGFR, CD31 and CD97." (PMID 22768192, 2012). "The ratio of CD44-KD and CD147-KD tumor volumes (DTX/VC) decreased faster in response to DTX or VC treatment, suggesting that the KD of either CD44 or CD147 can induce suppression of tumor development, compared to the scr and wild-type xenografts." (PMID 22870202, 2012). "Thus, both MCF-7 and R2d cells depend on estrogenic stimulation to form tumor, and respond to BBP with increased CD44 and decreased CD24." (PMID 22905168, 2012). "Similarly, HSPG (i.e., CD44) and other constituents of the ECM (i.e., fibronectin) are alternatively spliced, decisively mediating cell proliferation and tumor metastasis." (PMID 23251556, 2012). "In this study CD44, CD24, ABCG2, and EpCAM could be detected by flow cytometry in all the RB patient tumor samples." (PMID 22328825, 2012). "It was therefore postulated that the content of CD44+CD24-/low cells or, in other words, the proportion of BCSCs might be related to tumor aggressiveness and distant metastasis, but the relationship with axillary LN status was not well established." (PMID 23046710, 2012).
tumor (continued). "Although CD44 and ALDH are the most studied CSC markers, recent evidence supports the possibility that CSC, much like all tumor cells are heterogeneous in their genetic and expression signatures resulting in different phenotypes and varied capacities for tumorigenesis." (PMID 22876238, 2012). "In the current study, CD44 or CD147-KD xenografts treated with DTX, showed significant targeted areas with tumor islands and obviously reduced MVD, suggesting that DTX may have a similar anti-angiogenic function as seen in the EOC model." (PMID 22870202, 2012). "CD44 is involved in a diverse range of physiological and pathological processes including lymphocyte homing and activation, cell-ECM interactions, migration, tumour growth and metastasis." (PMID 22363471, 2012). "In VC-treated xenografts, a slightly stronger regression of tumor growth was seen in CD44 KD xenografts compared with CD147 KD xenografts, while no obvious difference was found between growth of CD44 KD and CD147 KD tumors (P>0.05)." (PMID 22870202, 2012). "Blocking the integrin receptors by RGD peptidomimetic agents or the peptide fragment of CD44 may be used to interfere with their respective OPN interactions, impairing tumor motility and survival." (PMID 22481923, 2012). "However, the CD44+ subpopulation presented major proportion in SKOV3 cells under both conventional culture conditions and tumor spheroids." (PMID 22643117, 2012). "Flow cytometric evaluation of spleens of mice that had rejected a secondary tumor rechallenge showed an enhancement in the CD4+CD44+ and CD8+CD44+ T cell memory markers as well as an enhanced secretion of IFNγ by memory T cells in response to OVA stimulation in vitro." (PMID 22815789, 2012). "CD44 interaction with hyaluronan induces ankyrin binding to MDR1 (P-glycoprotein), resulting in the efflux of chemotherapeutic agents and chemoresistance in tumor cells." (PMID 23213537, 2012). "Metastatic lesions were found in the lungs of mice inoculated into the mammary fat pad with CD44/Sca1+ cells but not observed in mice injected in a similar way with CD44/Sca1- tumor cells, regardless of donor age." (PMID 22277639, 2012). "Taken together with the differential expression of HER-2, these findings provides further evidence on the worse prognosis found in CD44+CD24-/low positive tumors, and might contribute to the more aggressive behavior of these neoplasms." (PMID 21824412, 2011). "CD44+ EOC stem cells express pluripotency markers such as β-catenin, Oct-4, and SSEA-4 and have been demonstrated to be the chemoresistant progenitors in vivo and are able to differentiate into the heterogenous cell types comprising the tumor." (PMID 21904548, 2011). "Thus, CSCs have been identified in a variety of solid malignancies with the identification of CSCs in these tumours being based on cell surface markers such as CD24, CD44, CD133 and Sca-1." (PMID 21468047, 2011). "Of CD44+CD24-/low positive tumours, 33% were grade 1 whereas only 23% of CD44+CD24-/low negative tumours were grade 1 (P = 0.006)." (PMID 22112299, 2011). "Furthermore, the expression of CD44 and CD133 decreased following chemotherapy in the majority of responsive tumours." (PMID 21829201, 2011). "Despite the requirement for IL-6 in mediating the tumor promoting abilities of fibroblasts, we found that IL-6 alone was not sufficient for expansion of CD44+/CD24−/EpCAM+ cells in the MCF7 cell line." (PMID 21957456, 2011). "Interestingly, exposure to PGE2 before CM collection significantly augmented the ability of tissue sample A to increase the percentage of CD44+/CD24−/EpCAM+ cells, suggesting that PGE2 enhanced fibroblast tumor promoting ability." (PMID 21957456, 2011). "Several cell surface markers, including CD24, CD44, CD133, CD166, EpCAM, or dye efflux assays have been used to sort populations of putative cancer stem cells from primary tumor cultures or cell suspensions obtained from tumor biopsies." (PMID 21264259, 2011).